HSD3B2 (hydroxy-delta-5-steroid dehydrogenase, 3 beta- and steroid delta-isomerase 2)
Diseases named in the same sentence as HSD3B2 in open-access papers:
HSD3B2 is named in the same sentence as 48 diseases in open-access papers, as found by Europe PMC text mining. Sharing a sentence is not in itself a finding about the gene and the disease. The quoted sentences say what the papers report.
congenital adrenal hyperplasia (14 papers, 2014 to 2025). Congenital adrenal hyperplasia (CAH) is an inherited endocrine disorder caused by a steroidogenic enzyme deficiency that is characterized by adrenal insufficiency and variable degrees of hyper or hypo androgyny manifestations, depending of the type and the severity of the disease. "Mutations in HSD3B2 gene cause a rare form of congenital adrenal hyperplasia with varying degree of salt wasting and incomplete masculinization, resulting from reduced production of corticoids and androgens." (PMID 39415787, 2024). "Deficiency caused by the mutations in HSD3B2 gene results in congenital adrenal hyperplasia (CAH) with salt-wasting (SW) and ambiguous genitalia, due to the reduction of glucocorticoid, mineralocorticoid and androgen." (PMID 39415787, 2024). "Mutations in the HSD3B2 gene that result in 3β-hydroxysteroid dehydrogenase type 2 deficiency are one rare underlying cause of congenital adrenal hyperplasia (CAH)." (PMID 36768194, 2023). "Salt losing 3-β-hydroxysteroid dehydrogenase deficiency (HSD3B2) is a rare form of congenital adrenal hyperplasia, seen in <0.5% of cases." (PMID 34055358, 2021). "Classical 3β-HSD deficiency due to mutations in the HSD3B2 gene is responsible for a rare form of congenital adrenal hyperplasia (CAH) and is identified by varying degrees of salt wasting." (PMID 32072793, 2020). "3beta-hydroxysteroid dehydrogenase type II deficiency (HSD3B2 deficiency), a rare form of congenital adrenal hyperplasia (CAH), is characterized by varying degrees of salt loss and incomplete masculinization in males and mild virilization or normal external genitalia in females." (PMID 36233635, 2022). "For instance, although both STAR and HSD3B2 mutations can lead to congenital adrenal hyperplasia (CAH), they result in markedly different profiles of hormone production and signaling." (PMID 41357796, 2025). "For example, studies using Star, Cyp11a1, and Hsd3b2 mutant mice have delineated critical steps in steroidogenesis that mirror the enzymatic defects seen in human congenital adrenal hyperplasia (CAH)." (PMID 41357796, 2025). "Congenital adrenal hyperplasia (CAH) is a group of autosomal recessive disorders caused by pathogenic variants identified in seven genes (CYP21A2, CYP11B1, CYP17A1, HSD3B2, StAR, POR, and CYP11A1) involved in the steroidogenesis pathway." (PMID 39451515, 2024). "Congenital adrenal hyperplasia (CAH) refers to a group of seven monogenic adrenal disorders, caused by pathological variants in genes coding for enzymes in the adrenal steroidogenic pathway: CYP21A2, CYP11B1, CYP17A1, HSD3B2, STAR, CYP11A1, and POR." (PMID 41450580, 2025). "Congenital adrenal hyperplasia (CYP21A2, CYP11B1, HSD3B2, CYP17A1, POR defects) constitutes the largest subgroup of impaired steroidogenesis and represents the most common cause of PAI in children." (PMID 27485500, 2016). "has shown that adrenal hyperplasia observed in IHA patients was immunoreactive for type I 3β-hydroxysteroid dehydrogenase (HSD3B1), whereas APA was immunoreactive for type II 3β-hydroxysteroid dehydrogenase (HSD3B2), not for HSD3B1." (PMID 25239966, 2014).
hypospadias (7 papers, 2016 to 2025). Hypospadias is the displacement of the urethral meatus on the ventrum of the penis. "In summation, we described a novel variant in the HSD3B2 gene with an autosomal recessive inheritance that probably affected fetal androgen synthesis and caused hypospadias in two siblings." (PMID 37384334, 2023). "A homozygous missense mutation of A82P in exon 3 of the HSD3B2 gene is also reported in a hypospadias patient." (PMID 37384334, 2023). "This is the first genetic study on hypospadias from the Yemen ethnicity and the second to report HSD3B2 mutations in more than one affected individual from the same family." (PMID 37384334, 2023). "HSD3B2 is related to the etiology of hypospadias and was reported as causative or contributory to hypospadias in earlier studies due to its role in the synthesis of endocrinal factors that regulate fetal urogenital system development." (PMID 37384334, 2023). "Additionally, its human homologs, HSD3B1 and HSD3B2, are associated with hypertension and hypospadias, further highlighting the importance of Hsd3b3 and its human counterparts in steroid hormone biosynthesis." (PMID 41293248, 2025). "Therefore, mutations of HSD3B2 underlie various types of hypospadias, as shown by the evidence of these earlier studies." (PMID 37384334, 2023). "Furthermore, the pathogenicity of the observed variant in this study, confirmed by multiple in silico tools, characterizes the influence HSD3B2 gene variants may have in the etiology of hypospadias." (PMID 37384334, 2023). "In patient 5, six variants in six genes were found: BNC2, FGF10, HSD3B2, IRX5, MAML2 and NOTCH2; all, except MAML2, have also been associated with hypospadias or gonadal development." (PMID 31555317, 2019). "In another study, HSD3B2 was genotyped in 90 hypospadias patients and 101 healthy controls." (PMID 37384334, 2023).
Adrenal insufficiency (5 papers, 2007 to 2025). Insufficient production of steroid hormones (primarily cortisol) by the adrenal glands. "Mutations in genes related to steroid biosynthesis (such as CYP11A1, CYP17A1, HSD3B2, HSD17B3, and StAR) will lead to androgen synthesis disorders with adrenal insufficiency besides the SRD5A2 gene mutation which results in the insufficient transformation of dihydrotestosterone from testosterone." (PMID 40247401, 2025). "The clinical differentials of sex reversal with adrenal insufficiency include P450scc deficiency due to mutations in CYP11A1 gene, Smith-Lemli-Opitz syndrome (DHCR7 gene), NR5A1 (SF1) mutation-related sex reversal, CYP17 and 3-beta hydroxysteroid dehydrogenase deficiency (HSD3B2 gene)." (PMID 23748066, 2013).
endometriosis (5 papers, 2020 to 2024). The growth of functional endometrial tissue in anatomic sites outside the uterine body. "The objective of that study was to examine whether infertility, associated with endometriosis, may result from disturbed expression of HSD3B2, HSD17B1, HSD17B2, and ESR1/2 genes." (PMID 33153202, 2020). "Higher expression and activity of HSD3B2 mRNA has been observed in endometriotic tissue compared to normal endometrium, indicating elevated E2 levels in endometriosis." (PMID 38603778, 2024). "Increased expression levels of HSD3B2 gene and of ESR1 gene were demonstrated in endometrium of infertile women with endometriosis." (PMID 33153202, 2020).
hyperandrogenism (5 papers, 2013 to 2022). Excessive secretion of androgens from the adrenal glands or gonads. "Interestingly, our previous research revealed that baicalin would potentially be an effective therapeutic agent for hyperandrogenism in PCOS by inhibiting the recruitment of GATA1 to the HSD3B2 promoter in ovarian tissue." (PMID 35600955, 2022). "SET played a positive role in regulating ovarian androgen biosynthesis by enhancing the transcription of steroidogenic enzymes CYP17A1 and HSD3B2, which maybe contribute to the hyperandrogenism in PCOS." (PMID 23421880, 2013). "Taken together, SET played a positive role in regulating ovarian androgen biosynthesis by enhancing transcription of CYP17 and HSD3B2, which may participate in hyperandrogenism of PCOS." (PMID 23421880, 2013). "SET played a positive role in regulating ovarian testosterone biosynthesis by enhancing the transcription of steroidogenic enzymes CYP17A1 and HSD3B2, which maybe contribute to the hyperandrogenism in PCOS." (PMID 23421880, 2013). "Because hyperandrogenism is a major pathophysiological feature of PCOS, we examined the excessive androgen generation resulting from hormone imbalances and CYP17A1 and HSD3B2 activity—key enzymes involved in steroidogenesis." (PMID 29757997, 2018). "A not uncommon presentation among adult women with mild hyperandrogenism is that they are found to have elevated serum DHEAS and/or reported to have “partial 3βHSD2D”, based on urine steroid profiling but with no HSD3B2 gene mutations identified." (PMID 30719691, 2019).
polycystic ovary syndrome (3 papers, 2013 to 2023). A disorder that manifests as multiple cysts on the ovaries. "Furthermore, specific overexpression of HSD3B2 has been found in the ovaries of women with polycystic ovary syndrome (PCOS), which is the most common endocrine disorder associated with hyperandrogenism and infertility in females." (PMID 23874725, 2013). "Therefore, specific downregulation of HSD3B2 at adrenarche around age 6–8 years and characteristic upregulation of HSD3B2 in the ovaries of women suffering from the polycystic ovary syndrome remain unexplained prompting us to study the regulation of HSD3B2 in adrenal NCI-H295R cells." (PMID 23874725, 2013). "Other studies demonstrated decreased expression of FSHR and CYP11A1 and increased expression of CYP19A1, STAR, HSD3B2 and INHBA in polycystic ovary granulosa cells compared to controls." (PMID 36768772, 2023).
adrenocortical carcinoma (2 papers, 2013 to 2021). "For our studies, we used the human adrenocortical carcinoma NCI-H295R cell line as our cell model expressing HSD3B2 and the human placental JEG3 cell line as the cell model expressing HSD3B1, but not HSD3B2." (PMID 23874725, 2013).
Hypertension (2 papers, 2018 to 2025). The presence of chronic increased pressure in the systemic arterial system. "Similarly, HSD3B2 promoter methylation highlights a potential mechanism by which HSD11β2 facilitates the pathogenesis of EH and glucocorticoid-induced hypertension." (PMID 29752343, 2018). "Consistently, we found that ACE methylation was lower in the hypertension group than in controls, whereas HSD3B2 methylation was higher in subjects with EH independent of HCMV infection." (PMID 29752343, 2018).
prostate carcinoma (2 papers, 2012 to 2020). A carcinoma that arises from epithelial cells of the prostate gland. "Specifically, two HSD3B2 SNPs in the 3′UTR (rs1819698 and rs1538989) were associated with significantly increased risk of prostate cancer in people of European descent (OR 2.66 95%CI 1.13–6.24)." (PMID 23284679, 2012). "Consistent with this, high prostatic 3β-HSD protein levels are correlated with several unfavorable clinical attributes in prostate cancer patients, while HSD3B2 transcript expression has been proposed as a potential prognostic biomarker in lung squamous cell carcinoma." (PMID 33187258, 2020).
21-hydroxylase deficiency (1 paper, 2021). "Since 21-hydroxylase deficiency is a much more prevalent disorder, differential diagnosis often includes testing both CYP21A2 and HSD3B2 genes, although in 46,XY patients, genital ambiguity is more suggestive of HSD3B2 deficiency." (PMID 37360892, 2021).
adenoma (1 paper, 2016). A neoplasm arising from the epithelium. "The ratio of CYP17A1 to HSD3B2 mRNA expression levels has been related to several endocrine diseases with a low level in APAs and high level in cortisol-producing adenomas." (PMID 27057163, 2016).
bladder cancer (1 paper, 2012). "We observed that genetic variation in the 3′UTR flanking region of the hormone regulation gene 3-beta-hydroxysteroid dehydrogenase type 2 (HSD3B2) was associated with nearly a two-fold increase in bladder cancer risk." (PMID 23284679, 2012). "Variants for a SNP in the hormone regulation gene 3-beta-hydroxysteroid dehydrogenase type II (HSD3B2) had an increased risk of bladder cancer (overall OR 1.94 95%CI 1.36–2.75) compared to those who were wildtype." (PMID 23284679, 2012). "The 3′UTR flanking variant form of the hormone regulation gene HSD3B2 was associated with increased bladder cancer risk in the New Hampshire population (adjusted OR 1.85 95%CI 1.31–2.62)." (PMID 23284679, 2012). "HSD3B2 SNP and bladder cancer risk in the New Hampshire population, by gender." (PMID 23284679, 2012). "HSD3B2 proxy SNP is associated with bladder cancer risk in the Texas population." (PMID 23284679, 2012). "The HSD3B2 SNP that we found associated was not included on the large genome-wide association panels used for the recent studies of bladder cancer." (PMID 23284679, 2012).
bone tumors (1 paper, 2019). "To determine enzalutamide responsiveness is related to androgen synthesis in bone tumors, we evaluated the expression of key enzymes in androgen synthesis, AKR1C3, HSD3B1 and HSD3B2, in bone tumors." (PMID 31638934, 2019). "Western blotting analyzed VCaP bone tumor samples for ERG, AR, AKR1C3 and HSD3B1 and HSD3B2 expression." (PMID 31638934, 2019).
chronic kidney disease (1 paper, 2024). Impairment of the renal function secondary to chronic kidney damage persisting for three or more months. "This study delves into the intricate relationship between the 3β-hydroxysteroid dehydrogenase type 2 enzyme (HSD3B2), the steroid hormone biosynthesis pathway, and chronic kidney disease (CKD)." (PMID 39525849, 2024).
Conn's syndrome (1 paper, 2025). "The findings indicated that the aldosterone‐producing enzymes HSD3B2 and CYP11B2 were both upregulated in Conn's syndrome and non‐functional ACAs, suggesting that hormone synthesis and secretion abnormalities are associated with ACAs." (PMID 40190189, 2025).
COVID-19 (1 paper, 2023). A disease caused by infection with severe acute respiratory syndrome coronavirus 2. "Endocrine-specific genes (e.g., HSD3B2, INS, IAPP, TSHR, FOXE1, LEP, and CRYGD) were deregulated in COVID-19 cases in an organ-specific manner." (PMID 37246981, 2023).
HCMV infection (1 paper, 2018). "Moreover, HCMV infection results in decreased ACE and increased HSD3B2 methylation." (PMID 29752343, 2018).
melanoma (1 paper, 2020). A malignant, usually aggressive tumor composed of atypical, neoplastic melanocytes. "Human melanoma tissues represented a prominent steroidogenic tumor type, expressing CYP11A1, HSD3B1, HSD3B2, CYP17A1, CYP21A1, and CYP11B1 and not expressing CYP11B2." (PMID 32680985, 2020).
metastatic prostate carcinoma (1 paper, 2022). A carcinoma that arises from the prostate gland and has spread to other anatomic sites. "Increases in oncogenic AR activity may be driven by somatic changes that upregulate crucial APUC genes in the metastatic prostate cancer tumors, such as HSD3B2 (1.8-fold increase) and SRD5A1 (2.1-fold increase)." (PMID 37435458, 2022).
metastatic tumors (1 paper, 2024). "Of the many APUC genes that have been associated with the activation of AR, we found that 6 (HSD3B1, HSD3B2, CYP11A1, CYP11B1, CYP17A1, and CYP3A43) exhibit robust association in prostate and metastatic tumors and were mutually exclusive with heightened AR activity." (PMID 39207857, 2024). "Six APUC genes (HSD3B1, HSD3B2, CYP3A43, CYP11A1, CYP11B1, CYP17A1) exhibited coalescent gene behavior in a cohort of metastatic tumors (n = 208)." (PMID 39207857, 2024).
non-small cell lung carcinoma (1 paper, 2024). A group of at least three distinct histological types of lung cancer, including non-small cell squamous cell carcinoma, adenocarcinoma, and large cell carcinoma. "Referring to a prior study on non-small cell lung cancer regarding in situ production of progesterone, we further observed whether the steroidogenic enzymes (StAR, CYP11A1, HSD3B2) are present and functional in PDAC cells." (PMID 38424455, 2024).
Premature ovarian insufficiency (1 paper, 2019). Amenorrhea due to loss of ovarian function before the age of 40. "Case Report: Whole exome sequencing revealed an extremely rare homozygous nonsense mutation in exon 2 of the HSD3B2 gene, leading to a premature stop codon (NM_000198.3: c.15C>A, p.Cys5Ter) in a patient with AAD and premature ovarian insufficiency." (PMID 31611844, 2019).
primary adrenal insufficiency (1 paper, 2021). A hormonal disorder that occurs when the adrenal glands fail to release adequate amounts of glucocorticoids (cortisol), mineralocorticoids (aldosterone, 11-deoxycorticosterone), and androgens (dehydroepiandrosterone) to meet physiologic needs, despite release of ACTH from the pituitary. "Importantly, the findings from the urinary steroid profiling analysis were instrumental in excluding other causes of primary adrenal insufficiency (i.e. mutations in NR5A1, StAR, CYP11A1 or HSD3B2)." (PMID 34524979, 2021).
tumor (6 papers, 2013 to 2025). "HSD3B2 plays a crucial role in steroid hormone biosynthesis and it is up-regulated in a relevant fraction of PCa that are characterized by an adverse tumour phenotype, increased androgen receptor signalling and early biochemical recurrence." (PMID 33509203, 2021). "Notably, several key genes involved in steroid synthesis, including CYP11B2, CYP21A2, and HSD3B2, were significantly upregulated along the trajectories toward the tumor cell lineage." (PMID 40190189, 2025). "Recent clinical observations have revealed predominant expression of HSD3B2 mRNA and protein in tumor cells of aldosterone-producing adenoma (APA), and HSD3B1 mRNA significantly correlated with CYP11B2 mRNA levels and plasma aldosterone concentrations in APA patients." (PMID 27057163, 2016). "The median CYP11A1 mRNA level in the CRPC metastases was 0.41 times compared to the level in the primary tumor tissue (P = 0.011), while the CYP17A1 and HSD3B2 mRNA levels in CRPC bone metastases were not significantly different from levels in the primary tumor tissue." (PMID 24244276, 2013).
cancer (3 papers, 2023 to 2025). A tumor composed of atypical neoplastic, often pleomorphic cells that invade other tissues. "Altogether, HSD3B1, HSD3B2, CYP11A1, CYP11B1, CYP17A1, and CYP3A43, hereby defined as APUC-6, demonstrated tissue- and cancer stage–specific interactions, with the most notable interaction in metastatic PC." (PMID 39207857, 2024).
cardiovascular diseases (1 paper, 2023). "Notably, mRNAs for most genes associated with cardiovascular diseases (e.g., HSD3B2, PPARG, NLN and CEACAM1) were downregulated in the colons of HBP subjects." (PMID 36768972, 2023).
HSD3B2 also shares sentences with these, for which no sentence is quoted: 3-beta hydroxysteroid dehydrogenase deficiency (2 papers); adrenocortical tumors (2); infertile (2); adrenal hypoplasia (1); adrenoleukodystrophy (1); campomelic dysplasia (1); congenital hypogonadotropic hypogonadism (1); cryptorchidism (1); electrolyte imbalances (1); endocrine diseases (1); hypogonadotropic hypogonadism (1); hypopituitarism (1); lung squamous cell carcinoma (1); Micropenis (1); mineralocorticoid insufficiency (1); Opitz syndrome (1); preeclampsia (1); primary ovarian insufficiency (1); secondary hypertension (1); seminoma (1); Smith-Lemli-Opitz syndrome (1); viral infection (1).